ACHE (acetylcholinesterase (Yt blood group))
Diseases named in the same sentence as ACHE in open-access papers (continued):
Sharing a sentence is not in itself a finding about the gene and the disease.
schistosomiasis (8 papers, 2016 to 2025). An infectious disease caused by parasitic trematodes of the genus Schistosoma that colonize human blood vessels and release eggs that can cause granulomatous reactions leading to acute (swimmer's itch or acute schistosomiasis syndrome) or chronic disease. "Since any new therapy for schistosomiasis should ideally target all three medically important species, we previously looked for evidence of surface AChE activity in S. japonicum and S. haematobium, in addition to S. mansoni." (PMID 40076600, 2025). "Despite this, the fact that AChE inhibition has been used to successfully treat schistosomiasis reinforces the notion that the identification of novel, safe, schistosome-specific AChE inhibitors deserves renewed attention." (PMID 40076600, 2025). "It has long been known that human schistosomiasis can be successfully treated by using chemicals that block AChE activity." (PMID 40076600, 2025). "We have identified and characterized a molecularly defined target to treat schistosomiasis, namely the tegumental AChE enzyme, SmTAChE." (PMID 40508222, 2025). "Since any new therapy for schistosomiasis should ideally target all three medically important species, we looked for evidence of surface AChE activity in S. japonicum and S. haematobium, in addition to S. mansoni." (PMID 36798133, 2023). "Because of its important motoneuronal function, AChE is seen as a possible target for drugs against schistosomiasis, because many schistosomes, such as S. mansoni, S. haematobium, S. bovis, and S. japonicum do express AChE." (PMID 33042153, 2020). "The results obtained further support the potential of AChE as a future drug or vaccine target against S. japonicum infection and also strengthen the view that immunological targeting of schistosome AChEs may be a suitable avenue for developing future treatments and the prevention of schistosomiasis." (PMID 30115897, 2018). "The results we present support the potential of AChE as a future drug target against S. japonicum and also strengthens the view that immunological targeting of schistosome AChEs may be a highly suitable avenue for future vaccine development and the prevention of schistosomiasis." (PMID 27283196, 2016). "In this study, we identified and characterized a molecularly defined target for schistosomiasis treatment, namely, tegumental, non-neuronal AChE (SmTAChE)." (PMID 40076600, 2025). "Notably, compound #2 preferentially inhibited rSmTAChE (IC50 = 0.74 μM) over human AChE (IC50 = 151 μM), thus providing a foundation for developing parasite-specific therapies targeting SmTAChE and potentially leading to new treatments for schistosomiasis." (PMID 40076600, 2025).
schizophrenia (8 papers, 2023 to 2025). A major psychotic disorder characterized by abnormalities in the perception or expression of reality. "For these reasons, the comparison of AChE inhibitors and antipsychotics in experimental schizophrenia models has been the center of attention." (PMID 39728751, 2024). "This suggests alendronic acid could be beneficial for schizophrenia via its effect on AChE." (PMID 38321095, 2024). "In contrast to the schizophrenia group in our study, EGCG–SeNPs modulated the neurotransmitters by increasing glutamate and GABA and decreasing SE, DA, and AChE." (PMID 41170387, 2025). "A meta-analysis revealed that adding AChE inhibitors such as donepezil, galantamine, or rivastigmine to antipsychotics can improve negative symptoms in patients with schizophrenia." (PMID 39337126, 2024).
mental disorder (7 papers, 2014 to 2025). A disease that has its basis in the disruption of mental process. "In the present study, acute exposure to AChE inhibitor insecticide remained significantly associated with pancreatic cancer risk even after adjusting for mental disorders as covariates in multivariable analyses." (PMID 41149448, 2025). "Numerous mental illnesses have been linked to AChE and MAO dysfunctions." (PMID 40365086, 2025). "Considering the high prevalence of mental disorders among individuals with acute exposure to AChE inhibitor insecticides, these findings underscore the importance of pancreatic cancer surveillance in this particularly vulnerable population." (PMID 41149448, 2025). "to control nervous system and mental disorders, studying the inhibitory action of C. ladanifer labdanum on acetylcholinesterase (AChE) activity is relevant." (PMID 38792084, 2024). "Therefore, people regularly exposed to toxins through inhalation and skin contact in agriculture may reduce the activity of acetylcholinesterase (AChE) in them, which can bring about mental disorders such as depression and suicide attempts." (PMID 39170219, 2024). "Despite rather low inhibitory activities against DAAO, AChE and BuChE, it seems that compounds with potent free-radical scavenging properties may play a supporting role in the treatment of neurodegenerative and psychiatric diseases." (PMID 25271427, 2014). "Our results also agree with the fact that neuropsychiatric manifestations are not observed in patients with the lowest degree of AChE inhibition (22%), demonstrating that this study supports the relationship between psychiatric disorders and exposure to OPs." (PMID 30813607, 2019).
autism (6 papers, 2014 to 2025). Persistent deficits in social interaction and communication and interaction as well as a markedly restricted repertoire of activity and interest as well as repetitive patterns of behavior. "Chlorpyrifos, an organophosphate insecticide known to inhibit AChE, is thought to be associated with autism risk and has shown DNT effects on oligodendrocyte differentiation and myelin formation at concentrations below those that cause systemic toxicity due to AChE inhibition." (PMID 34360696, 2021). "The Changes in AChE expression have also been reported in other rodent models of valproic-acid-induced autism." (PMID 40806421, 2025).
behavioral disorders (6 papers, 2016 to 2024). "Acute exposure to 2 μg/L DM caused a significant decrease in the AChE activity in the brain, liver, and muscle tissue of silver carp (Hypophthalmichthys molitrix), resulting in behavioral disorders." (PMID 39916965, 2024). "Our results also confirmed that muscle AChE inhibition in zebra fish is a factor disorder in swimming behavior and there is also a 2 h delay between AChE inhibition and the behavior disorder." (PMID 27999812, 2016).
brain tumors (6 papers, 2012 to 2025). "The fraction densities and associated AChE activities were consistent with exosomes isolated from other cell types including murine brain tumor cells." (PMID 22848702, 2012). "Some research questions the utility of AChE as an EV marker, at least in blood EV products, but numerous brain tumors nonetheless express AChE." (PMID 39585062, 2024). "Increased AChE and BChE activity was also observed in brain tumors, including GBM." (PMID 34959693, 2021). "Bioinformatic analysis has shown that AChE is connected to proteins in the PI3K/Akt pathway, which promotes anti-apoptotic and proliferative effects in brain tumors." (PMID 40475540, 2025).
Cirrhosis (6 papers, 2012 to 2022). A chronic disorder of the liver in which liver tissue becomes scarred and is partially replaced by regenerative nodules and fibrotic tissue resulting in loss of liver function. "ACHE expression has been shown to be downregulated in human HCCs5 and lower Ache levels have been implicated also, in cirrhosis induction in a rat model." (PMID 29371671, 2018). "For instance, a marked decrease in the AChE levels was previously observed in rat livers with cirrhosis." (PMID 36548550, 2022). "Activity of serum AChE could be an index of liver function and low activity of the enzyme has been reported in so many liver dysfunctions like jaundice and cirrhosis." (PMID 25821630, 2015). "Thus, it is plausible that AChE participates in hepatocellular apoptosis that characterizes cirrhosis." (PMID 23028565, 2012). "Thus, serum AChE activity could be a liver function indicator, and decreased enzyme activity was recorded in several liver disorders such as cirrhosis and jaundice." (PMID 32517066, 2020). "Studies in patients with liver cirrhosis have found an increase in AchE activity in the brain, while in TAA-induced model of cirrhosis the activity of AchE was found to be elevated in enthorinal cortex, nc." (PMID 26241899, 2015).
congenital myasthenic syndrome (6 papers, 2016 to 2025). Congenital myasthenic syndrome (CMS) is a group of genetic disorders of impaired neuromuscular transmission at the motor endplate characterized by fatigable muscle weakness. "ColQ deficiency brings to a drastically decreased AChE localization at NMJs, causing congenital myasthenic syndrome with AChE deficiency." (PMID 28082868, 2016). "Compared to D, the separation between phases is less visible in C. The ColQ mouse is a model of congenital myasthenic syndrome with AChE deficit at the neuromuscular junctions." (PMID 37288430, 2023). "ColQ-deficient mutant mice lack clusters of AChE at the NMJ and congenital myasthenic syndromes associated with AChE deficiency are caused by recessive mutations in ColQ." (PMID 31269763, 2019). "Another example of excitotoxic damage happens in the muscular endplate due to rare genetic disorders, such as congenital myasthenic syndromes (CMS; Grassi and Fucile, 2020), which involves mutations in the genes of proteins related to neuromuscular transmission, mostly (about 15%) AChE gene." (PMID 40740969, 2025). "So far, no mutation has been identified in the ACHE human gene but over 50 different mutations in the COLQ gene are causative for a congenital myasthenic syndrome (CMS) with AChE deficiency." (PMID 33362463, 2020).
gastric cancer (6 papers, 2014 to 2025). A primary or metastatic malignant neoplasm involving the stomach. "Gastric cancer cells were treated with AChE delivered by replication-deficient adenoviral vector (Ad.AChE) or oncolytic adenoviral vector (ZD55-AChE), respectively, followed by measurement of cell viability and apoptosis by MTT assay and apoptosis detection assays." (PMID 25220382, 2014). "The potent anti-tumour action that an AChE-loaded adenoviral vector exerts on gastric cancer cells lends support to the tumour growth-promoting facet of ACh." (PMID 25956553, 2015). "The AGS cell growth and another gastric cancer cell line NCI-N87 cell growth were significantly inhibited by Ad.AChE at a high MOI level (100 or 200)." (PMID 25220382, 2014). "Ad.AChE and ZD55-AChE inhibited gastric cancer cell growth, and low dose of ZD55-AChE induced mitochondrial pathway of apoptosis in cells." (PMID 25220382, 2014). "Activated AChE protein was expressed in Ad.AChE-infected gastric cancer cell line AGS cells, and can be secreted to culture medium." (PMID 25220382, 2014). "Overexpression of AChE by an oncolytic adenoviral vector (ZD55-AChE) significantly inhibited gastric cancer cell proliferation and reduced growth of gastric tumors in mice." (PMID 25220382, 2014). "A positive correlation was found between higher level of AChE expression in gastric cancer patient samples and longer survival time of the patients." (PMID 25220382, 2014). "In vivo, the tumor growth of gastric cancer xenografts in mice treated with Ad.AChE or ZD55-AChE (1 × 109 PFU) were measured." (PMID 25220382, 2014). "Similarly, gastric cancer patients with high AChE levels also demonstrated better overall survival, and the low AChE expression decreased overall survival." (PMID 37760598, 2023). "Finally, in hepatic tumors, gastric cancer, and head and neck carcinomas, a significant decrease in AChE activity was found." (PMID 37760598, 2023). "In addition, the cell viability of gastric cancer stem cells treated with Ad.AChE or ZD55-AChE were evaluated by MTT assay." (PMID 25220382, 2014). "Here, we reported the effect of AChE on gastric cancer therapy." (PMID 25220382, 2014). "In addition, gastric cancer patients with higher AChE expression levels exhibited longer survival time." (PMID 25220382, 2014). "In our work, lower expressed AChE protein was found in gastric cancer tissues than adjacent non-cancerous tissues." (PMID 25220382, 2014). "Relatively lower expression level of AChE was observed in gastric cancer tissues compared to the adjacent non-cancerous tissues." (PMID 25220382, 2014). "Gastric cancer samples presented a low AChE expression compared to the non-cancerous samples, and patients with higher AChE levels showed a longer survival." (PMID 25220382, 2014).
ischemia (6 papers, 2012 to 2023). A hypoperfusion of the BLOOD through an organ or tissue caused by a PATHOLOGIC CONSTRICTION or obstruction of its BLOOD VESSELS, or an absence of BLOOD CIRCULATION. "Besides, miR-132 enhances the cholinergic blockade of the inflammatory response by targeting acetylcholinesterase (AChE), which also inhibits the activation of pro-inflammatory microglia and provides protection against neuronal death caused by ischemia." (PMID 34025674, 2021). "It was reported that miR-132 enhanced cholinergic blockade of inflammatory responses and protected against ischemia-induced neuronal cell death by targeting acetylcholinesterase (AChE)." (PMID 37637999, 2023). "A similar finding of a rapid increase in astroglial acetylcholinesterase (AChE) gene expression (a two- to three-fold increase in readthrough-AChE within 1 h post-ischemia) has been described previously." (PMID 22761937, 2012). "However, one study showing that donepezil improves muscle atrophy in a mouse model of ischemia paves the way to future investigations on the effect of this and other AChE inhibitors on sarcopenia in Tg2576 mice." (PMID 34573265, 2021). "The herein observed combined upregulation of AChE together with mAChR-M1 downregulation bears the potential to critically blunt cholinergic signaling, the integrity of which appears crucial in the adaptive response to ischemia." (PMID 34359879, 2021).
pancreatic cancer (6 papers, 2014 to 2025). "Although pancreatic cancer incidence is generally higher in men than in women, this study revealed a fivefold increase in risk among women after acute exposure to AChE inhibitor insecticide." (PMID 41149448, 2025). "Despite the biological plausibility and accumulating evidence linking chronic pesticide exposure to cancer, no population-based cohort study has assessed the long-term risk of pancreatic cancer after acute exposure to high-dose AChE inhibitor insecticide." (PMID 41149448, 2025). "The observed adjusted HR of 2.57 for acute exposure to AChE inhibitor insecticide indicates a substantial association with pancreatic cancer, underscoring its potential clinical and public health significance as a critical risk factor." (PMID 41149448, 2025). "Acute high-dose exposure to AChE inhibitor insecticide was associated with an increased risk of pancreatic cancer (adjusted HR: 2.57)." (PMID 41149448, 2025). "Acute high-dose exposure to AChE inhibitor insecticide may increase the risk of pancreatic cancer." (PMID 41149448, 2025). "Dr. Demir’s group demonstrated that in pancreatic cancer with high AChE expression, the inhibition of AChE or the administration of ACh reduced both TAM infiltration and serum pro-inflammatory cytokine levels." (PMID 37760598, 2023). "Physostigmine, a reversible AChE inhibitor, for example, has been shown to reduce pancreatic cancer cell viability and invasion, macrophage infiltration, and pro-inflammatory signals through the inhibition of intrinsic AChE activity." (PMID 34500749, 2021). "These carcinogenic effects of acute exposure to AChE inhibitor insecticide, which may persist after hospital discharge, could synergistically contribute to the onset of pancreatic cancer across a patient’s lifetime." (PMID 41149448, 2025). "Although this study demonstrated an association, it did not establish causality between acute exposure to AChE inhibitor insecticide and pancreatic cancer." (PMID 41149448, 2025). "Given the poor prognosis of pancreatic cancer and the unique exposure profile in South Korea, this study aimed to assess whether acute AChE inhibitor insecticide exposure increases the subsequent risk of pancreatic cancer and to identify potentially high-risk subgroups." (PMID 41149448, 2025). "Given that acute exposure to AChE inhibitor insecticide was the inclusion criterion and pancreatic cancer was the primary outcome, the relatively small number of pancreatic cancer cases observed in our cohort may reflect the inherent epidemiologic characteristics." (PMID 41149448, 2025).
asthma (5 papers, 2008 to 2020). "Noteworthy, estradiol protects airways of experimental hyperresponsiveness since it increases airways AChE activity as well as prevents mucus and collagen deposition in asthma models." (PMID 20735828, 2010). "It has been proposed that organophosphorus pesticide–induced asthma is mediated by inhibition of AChE, the enzyme that degrades acetylcholine." (PMID 18335107, 2008). "Moreover, our results indicated that the AChE in the lungs of the asthma model animals maintained the equivalent ACh degradative activities relative to the normal mice." (PMID 32367293, 2020). "However, AChE inhibitors including huperzine A should be used cautiously for AD patients with cardiovascular disease, asthma, and intestinal obstruction." (PMID 30941041, 2019). "In previous asthma studies, AChE activity levels were quite sensitive to the sensitisation protocols and model types; therefore, ACh changes may occur by a slightly different mechanism in other asthma model animals." (PMID 32367293, 2020). "Organophosphorus pesticides, at environmentally relevant concentrations that do not inhibit acetylcholinesterase (AChE), may precipitate asthma in humans and cause airway hyperreactivity, a key feature of asthma, in guinea pigs." (PMID 18335107, 2008). "To investigate the mechanism of the effects of BAW on cholinergic regulation of airway inflammation and remodeling, we measured changes in AChE activity and the AChR M3 downstream signaling pathway in airway tissue of an OVA-induced asthma model." (PMID 30360392, 2018).
colitis (5 papers, 2015 to 2023). Inflammation of the colon. "In the present study, according to macroscopic, microscopic and biochemical evaluations, ACAE and ACHE had protective effects against acetic acid-induced colitis in rats." (PMID 32995327, 2020). "False positive staining is seen occasionally in hemorrhagic specimens (due to the high concentrations of AChE in the red blood cell membrane), in colitis and in intestinal neuronal dysplasia." (PMID 26631177, 2015). "In dextran sulfate sodium (DSS)-induced colitis, central activation of the vagus nerve by galantamine, an AChE inhibitor, reduced the severity of DSS-induced colitis in mice." (PMID 34307422, 2021). "In the model of mice colitis, we also found that p-STAT3 and AChE increased expressed in intestinal CD68-positive cells in DSS mice compared with sham ones." (PMID 27977009, 2016).